RET (ret proto-oncogene)
Diseases named in the same sentence as RET in open-access papers (continued):
Sharing a sentence is not in itself a finding about the gene and the disease.
medullary thyroid carcinoma (continued). "Medullary thyroid carcinomas have been found to overexpress proto-ret mRNA, indicating RET overexpression as one of the main players in the tumor’s pathophysiology." (PMID 38673496, 2024). "Alterations in the RET gene are key drivers of papillary and medullary thyroid carcinoma tumorigenesis." (PMID 39458944, 2024). "An elderly male in his 70s with a history of RET-fusion positive medullary thyroid cancer with known liver metastases presented to the emergency department with worsening malaise, high fevers, hypotension, and a cutaneous eruption of 2 days duration." (PMID 39148638, 2024). "It was reported that RET expression played a crucial role in the survival, proliferation, and anoikis resistance of medullary thyroid carcinoma cells." (PMID 38957390, 2024). "ARROW was a global phase I/II trial of pralsetinib in patients with medullary thyroid cancer, RET-altered NSCLCs, and other RET-altered solid tumors." (PMID 39199650, 2024). "In the context of sporadic medullary thyroid carcinoma (MTC), somatic mutations in the RET gene have been detected in a substantial proportion, ranging from 43 to 71%." (PMID 39439561, 2024). "The RET (rearranged during transfection) is a well-known gene involved in the development and progression of several types of cancers, particularly medullary thyroid cancer and multiple endocrine neoplasia type 2 (MEN 2)." (PMID 37623222, 2023). "Medullary thyroid carcinoma (MTC) cells, which are neoplasms of the endocrine system, account for 10% of all thyroid cancers and are mainly caused by mutations in the RET proto-oncogene from para-follicular C-cells." (PMID 37623229, 2023). "In the context of RET-mutant medullary thyroid carcinoma (MTC), it is recommended to use selpercatinib as a kinase inhibitor targeting various forms of rearranged during transfection (RET), including wildtype RET, multiple mutated RET isoforms, VEGFR1, and VEGFR3." (PMID 37623229, 2023). "Gain-of-function RET pathogenic variants are potent oncogenic drivers and are associated with multiple endocrine neoplasia type 2 (MEN2) as well as sporadic medullary thyroid carcinoma (MTC)." (PMID 37626640, 2023). "MEN2A is caused by activating variants in the proto-oncogene RET and typically presents as medullary thyroid carcinoma, pheochromocytoma, and parathyroid tumours (20-30%) with a lower penetrance." (PMID 37810884, 2023). "The latest AFIRMA Genomic Sequencing Classifier is based on RNA sequencing and analysis of BRAFV600E mutations, RET/PTC1 or RET/PTC3, and specific alterations characteristic of parathyroid lesions, medullary thyroid cancer, and Hürtle cell lesions." (PMID 37512489, 2023). "In RET-mutant medullary thyroid cancer, the overall response rate was 71% in first line treatment and 60% in the second line." (PMID 36980956, 2023). "In RET-mutant medullary thyroid cancer, the overall response rate was 73% in first line treatment and 69% in the second, also showing it to be effective on CNS metastases and uncommon metastatic sites such as choroidal metastases." (PMID 36980956, 2023). "The RET gene plays a role in the development of medullary thyroid carcinoma (MTC) as part of multiple endocrine neoplasia type 2 (MEN2) syndrome." (PMID 37046823, 2023). "FDA approved vandetanib, which primarily inhibits the RET tyrosine kinase signaling pathway, to treat advanced medullary thyroid carcinoma." (PMID 36582799, 2022). "TAS0953/HM06 is a novel, small-molecule RET-TKI that can inhibit RET-associated NSCLC, papillary and medullary thyroid cancer, and several other solid tumors." (PMID 36557971, 2022). "RET mutations associate with the multiplex endocrine neoplasia type 2 (MEN2) syndrome, which is characterized by the development of medullary thyroid cancer, parathyroid tumors and PCC." (PMID 35163370, 2022).
medullary thyroid carcinoma (continued). "In 2020, the first highly RET-selective kinase inhibitor (Selpercatinib) was approved for the treatment of RET-mutant medullary thyroid carcinoma, showing marked and durable antitumor activity." (PMID 35985422, 2022). "MEN 2 is caused by missense, heterozygous, gain-of-function variants in the RET protooncogene (OMIM 164761) and is associated with an increased risk for medullary thyroid cancer." (PMID 35668420, 2022). "The ARROW trial also enrolled 122 patients with RET-mutant medullary thyroid carcinoma and 20 with RET fusion-positive thyroid cancer." (PMID 36557971, 2022). "Ret Proto-oncogene (RET) expression was suppressed by berberine by more than 90% in medullary thyroid carcinoma cells at a concentration of 2.5 μg/mL." (PMID 36144625, 2022). "Bortezomib is an inhibitor for proto-oncogene RET has been approved for treatment of medullary thyroid cancer." (PMID 35692574, 2022). "As discussed in sections 4.2 and 4.3, aberrant RET activation is frequently found in neuroendocrine tumors such as papillary and medullary thyroid cancers." (PMID 35957881, 2022). "RET gain-of-function point mutations are driver events in multiple endocrine neoplasia 2 (MEN2) syndrome and in sporadic medullary thyroid cancer, while RET rearrangements are driver events in several non-medullary thyroid cancers." (PMID 36091144, 2022). "For example, selpercatinib and pralsetinib inhibit mutant RET in medullary thyroid cancer but they can also block the RET fusion proteins-mediated signaling found in PTC." (PMID 36605433, 2022). "About 20% of MTC results from inherited genetic abnormalities (RET gene) known as familial medullary thyroid carcinoma." (PMID 35204408, 2022). "BBR inhibited RET expression in medullary thyroid carcinoma (MTC) cells by more than 90% at a concentration of 2.5 μg/mL but did not affect TPC1 cells." (PMID 34885950, 2021). "Vandetanib, targeting VEGFR, epidermal growth factor receptor (EGFR), RET, for medullary thyroid cancer." (PMID 34956857, 2021). "In humans, mutations in the RET gene are associated with the pathogenesis of various forms of diseases that include Hirschsprung’s disease (HSCR) and medullary thyroid carcinoma (MTC)." (PMID 33958373, 2021). "Here, the anti-tumor activity of a novel RET inhibitor was characterized in medullary thyroid carcinoma cells." (PMID 33419162, 2021). "Germline mutations that activate RET activity have been associated with multiple endocrine neoplasia 2 (MEN 2), which consists of three primary tumor types (medullary thyroid cancer, pheochromocytoma, and parathyroid hyperplasia or adenoma)." (PMID 33771190, 2021). "Conversely, medullary thyroid cancer (MTC) occurs in the neuroendocrine parafollicular cells (C cells), and is solely induced by RET proto-oncogene mutations." (PMID 34062862, 2021). "In a clinical phase 1 study, it showed a 77% overall response rate in RET fusion-positive cancers, with intracranial activity and a 45% overall response rate in RET-mutant medullary thyroid cancer." (PMID 34832869, 2021). "Several RET-targeting inhibitors were developed and showed durable anti-tumor efficacy in RET-altered medullary thyroid cancer." (PMID 34221969, 2021). "Two patients with an RET mutation had bilateral PCC and underwent total thyroidectomy because of medullary thyroid carcinoma." (PMID 33584544, 2020). "In medullary thyroid cancer cells, nelfinavir decreased the expression of RET and its downstream signaling effectors Akt, ERK1/2 and p70S6K." (PMID 33228205, 2020). "By comparison, the vast majority of MTC in the pediatric population are hereditary, the result of germline RET mutations resulting in multiple endocrine neoplasia (MEN) type 2A syndrome (90–95% of childhood MTC), MEN type 2B, or familial medullary thyroid carcinoma (FMTC)." (PMID 31540418, 2019).
medullary thyroid carcinoma (continued). "Gain-of-function germline heterozygous RET mutations cause multiple endocrine neoplasia type 2 (MEN 2), characterized by medullary thyroid carcinoma and pheochromocytoma." (PMID 29684080, 2018). "Medullary thyroid carcinomas (MTCs) are rare thyroid tumors occurring in both sporadic and hereditary forms, whose pathogenesis is related to RET proto-oncogene alterations." (PMID 29642647, 2018). "Medullary Thyroid Cancer (MTC) whose pathogenesis is strictly related to RET proto-oncogene alterations, has been shown to have a heterogenic RET mutation profile in subpopulations of MTC." (PMID 29515777, 2018). "RET gene mutations were also found in 97% of patients with MEN2A, who have an increased risk for parathyroid adenoma or hyperplasia, medullary carcinoma of the thyroid, and pheochromocytoma." (PMID 29983117, 2018). "For example, approximately one in 1750 individuals was observed to harbor a pathogenic ret proto-oncogene (RET) allele, compared with an estimated prevalence of MEN2/familial medullary thyroid cancer of approximately one in 80,000." (PMID 29308445, 2017). "BBR has been shown to inhibit the activity of the RET tyrosine in medullary thyroid carcinomas (MTC)." (PMID 28611316, 2017). "Interactions between EGFR and chimeric forms of RET found in 30-50% of sporadic medullary thyroid cancers (RET/PTCs) have been reported by Croyle et. al.." (PMID 28460442, 2017). "Medullary thyroid carcinoma (MTC) is a rare neuroendocrine tumor originating from parafollicular C cells of the thyroid and associated with mutations in the proto-oncogene REarranged during Transfection (RET)." (PMID 28658345, 2017). "Cabozantinib is another FDA-approved tyrosine kinase inhibitor targeting three important pathways: MET, vascular endothelial growth factor (VEGF), and rearranged during transfection (RET) for the treatment of metastatic medullary thyroid cancer." (PMID 27703281, 2016). "This retrospective multicenter study, centrally conducted and supported by the Society of Endocrinology and Metabolism of Turkey, aimed to evaluate the impact of free RET proto-oncogene testing in medullary thyroid carcinoma (MTC) patients." (PMID 26758973, 2016). "The RET inhibitor vandetanib shows antiproliferative activity in RET-mutant medullary thyroid cancer (MTC), and was recently approved by the US Food and Drug Administration for treatment of metastatic MTC." (PMID 26684754, 2015). "ALW-II-41-27, XMD15-44 and HG-6-63-01 inhibited proliferation of RET mutant medullary thyroid carcinoma cells with an IC50 of 1.0–5.7 nM." (PMID 26046350, 2015). "The present work aimed to examine the effects of three new drugs, RAF265, SB590885 and ZSTK474, on a RET-activated TT cell line model derived from an aggressive medullary thyroid carcinoma." (PMID 26081844, 2015). "Treatment with the RET inhibitor RPI-1 significantly reduced s2056 phosphorylation in RET cells as well as in a human medullary thyroid cancer cell line." (PMID 26065416, 2015). "Constitutive activation of the Rearranged during Transfection (RET) proto-oncogene leads to the development of MEN2A medullary thyroid cancer (MTC)." (PMID 26065416, 2015). "Medullary thyroid carcinoma (MTC) TT cell line has been used to evaluate the effects of berberine on RET expression and its downstream signaling pathways." (PMID 26307103, 2015). "Like most tumors with an activated RET proto-oncogene, medullary thyroid cancer is largely resistant to standard chemotherapy and radiation regimens." (PMID 26065416, 2015). "Several anti-RET TKIs have been identified and vandetanib and cabozantinib have been recently approved for locally advanced or metastatic medullary thyroid carcinoma treatment." (PMID 26046350, 2015). "We performed also one elective MINET-TTE due to hereditary burden of medullary thyroid carcinoma-positivity of RET proto-oncogene." (PMID 24800227, 2014).
medullary thyroid carcinoma (continued). "It is approved for use in medullary thyroid carcinoma, consistent with its potent inhibition of RET." (PMID 24651269, 2014). "Familial medullary thyroid cancer (FMTC) has been linked to mutations in exon 8 of the RET gene, but the association with phaeochromocytoma and MEN2A has only recently been discovered." (PMID 24616773, 2013). "Nearly one-third of pediatric RET gene carriers with increased basal calcitonin levels are believed to harbor occult medullary thyroid carcinoma." (PMID 23554805, 2013). "Medullary thyroid carcinoma (MTC) is a NET of thyroid parafollicular cells, with some 20% showing germline mutations of the RET oncogene." (PMID 24616764, 2013). "A clear association between Medullary Thyroid Carcinoma (MTC) and RET oncogene mutation has been accepted." (PMID 22676344, 2012). "Mutations in the RET proto-oncogene have been directly associated with MEN2 and hereditary medullary thyroid carcinoma, and provide guidance for patient care." (PMID 21479187, 2011). "There were 41 phosphotyrosine proteins detected downstream following RET activation from two different medullary thyroid cancer cell lines and the EGFR pathway was over-expressed." (PMID 24281099, 2010). "Germline mutations in RET are responsible for multiple endocrine neoplasia type 2 (MEN2), an autosomal dominantly inherited cancer syndrome that is characterized by medullary thyroid carcinoma (MTC), pheochromocytoma, and parathyroid hyperplasia/adenoma." (PMID 16707008, 2006). "This cohort study found that incidentally identified moderate-risk RET pathogenic variants are associated with substantially lower medullary thyroid cancer risk compared with clinically ascertained cases, with no excess mortality without intervention." (PMID 40577012, 2025). "In medullary thyroid cancer (MTC) with rearranged during transfection (RET) mutations, resistance to RET inhibitors may arise from secondary RET alterations and activation of bypass signaling pathways." (PMID 40843353, 2025). "A recent Phase 3 clinical trial has been published concluding that treatment with selpercatinib resulted in superior progression-free survival and treatment-free survival compared to other therapies such as cabozantinib or vandetanib in patients with RET-mutant medullary thyroid cancer." (PMID 39744583, 2025). "Most commonly, the first manifestation of MEN2 is medullary thyroid carcinoma, which strongly correlates with the underlying RET pathogenic variant (which is not the case in MEN1 for MEN1)." (PMID 40364143, 2025). "We therefore aimed to identify the frequency of pathogenic RET variants, the spectrum of variants, and their associated risks with medullary thyroid cancer and all-cause mortality without intervention in clinically unselected individuals." (PMID 40577012, 2025). "The clinical manifestation of multiple endocrine neoplasia type 2 (MEN2) in terms of developing medullary thyroid cancer (MTC), pheochromocytoma (PCC), and/or primary hyperparathyroidism (PHPT) is related to the respective pathogenic variant of the RET proto-oncogene." (PMID 38339246, 2024). "Although hyperparathyroidism and thyroid tumors have not been identified in this patient, the penetrance of medullary thyroid cancer in RET mutation-positive patients is 100%." (PMID 39559597, 2024). "Variants affecting the RET proto-oncogene, which encodes a receptor tyrosine kinase involved in cell growth and differentiation, are implicated in the development of medullary thyroid carcinoma (MTC) and its hereditary form, multiple endocrine neoplasia type 2 (MEN2)." (PMID 39512978, 2024). "Next-generation sequencing (NGS) analysis of sporadic medullary thyroid carcinoma (sMTC) has led to increased detection of somatic mutations, including RET M918T, which has been considered a negative prognostic indicator." (PMID 38660141, 2024).
medullary thyroid carcinoma (continued). "In addition, up to 70% of medullary thyroid cancers (MTC) show activating RET mutations, but RET fusions and mutations are rare in breast cancer." (PMID 39931212, 2024). "Also, the investigators detected three patients (11%) with G810X mutations (two patients with RET fusion + NSCLC) and Y806C (one patient with medullary thyroid carcinoma))." (PMID 39199650, 2024). "We compared the parametric and ML models and the results showed that the proposed ML approach is able to adequately predict patient OS across RET-altered solid tumors, including non-small cell lung cancer, medullary thyroid cancer as well as other solid tumors." (PMID 38919267, 2024). "For example, RET alterations were detected in 4 of 5 sampled medullary thyroid carcinomas (80%), 4 of 54 ovarian epithelial carcinomas (7.4%), and 27 of 527 lung carcinomas (5.1%), highlighting the rarity of RET alterations in breast cancer relative to other known RET-driven malignancies." (PMID 36918928, 2023). "Medullary thyroid cancer (MTC) is a rare disease, which can be either sporadic (roughly 75% of cases) or genetically determined (multiple endocrine neoplasia type 2, due to REarranged during Transfection RET germline mutations, 25% of cases)." (PMID 37835559, 2023). "RET is a proto-oncogene that has been implicated in PTC and medullary thyroid carcinoma (MTC)." (PMID 37444504, 2023). "Vandetanib and cabozantinib have become mainstay treatments for metastatic medullary thyroid cancer regardless of RET mutation status." (PMID 37434642, 2023). "Nonetheless, prophylactic surgery remains recommended in children harboring RET mutations (MEN syndromes) and at risk of medullary thyroid carcinoma (MTC) onset, with the timing of surgery determined by the known progression risk of every specific mutated codon." (PMID 37046700, 2023). "Rarely, patients present with typical physical features (mucosal neuromas, prominent corneal nerves and marfanoid body habitus) of MEN2B but without a RET gene mutation or associated endocrinopathies (medullary thyroid carcinoma or pheochromocytoma)." (PMID 37303040, 2023). "The remaining 79 tested patients were negative for germline pathogenic variants; however, 2 of these patients had a clinical diagnosis of MEN2A (PHEO and medullary thyroid carcinoma) but no germline RET pathogenic variants were identified." (PMID 37296853, 2023). "In doubt cases, as well as for screening RET gene carriers and to differentiate between C-cell hyperplasia and medullary thyroid cancer calcium gluconate stimulation test may be performed." (PMID 37198359, 2023). "RET germline gain-of-function mutations cause predisposition to multiple endocrine neoplasia 2 (MEN2) syndrome, while somatic RET mutations have been found in 40-65% of sporadic medullary thyroid cancers (MTCs)." (PMID 36091144, 2022). "The aim of our study was to investigate the association of common non-disease-causing RET variants with clinical outcome in the population of sporadic medullary thyroid carcinoma patients from southern Poland." (PMID 34769224, 2021). "The FDA (Food and Drug Administration) has approved several drugs targeting RET for the treatment of cancer for example, lenvatinib and sorafenib for differentiated thyroid cancers, and cabozantinib and vandetanib for medullary thyroid carcinomas." (PMID 33525725, 2021). "Recent studies reported that mutations at solvent front (G810R/S/C/V), hinge (Y806C/N) and β2 strand (V738A) sites within the RET kinase domain can mediate acquired resistance to selpercatinib and pralsetinib in RET fusion-positive NSCLC and in RET-mutant medullary thyroid cancer." (PMID 33806299, 2021). "In medullary thyroid cancer, miR-127 was more frequently upregulated in RET wild-type cancers." (PMID 33562573, 2021).